SERPING1 (serpin family G member 1)
Diseases named in the same sentence as SERPING1 in open-access papers (continued):
Sharing a sentence is not in itself a finding about the gene and the disease.
prostate carcinoma (6 papers, 2020 to 2025). A carcinoma that arises from epithelial cells of the prostate gland. "Serine proteinase inhibitor family G1 (SERPING1) downregulation was associated with poor prognosis in prostate cancer (PCa)." (PMID 35664768, 2022). "Another line of study has shown that decreased expression of SERPING1 can be a biomarker for risk of prostate cancer and prediction of malignant progression." (PMID 32024545, 2020). "In addition, levels of SERPING1 can provide a reference for low‐risk prostate cancer patients to accept active surveillance and reduce overtreatment." (PMID 39474998, 2025). "Serpin peptidase inhibitor family G1 (SERPING1) was identified as a novel marker in diagnosis and prognostic prediction in prostate cancer, indicating a strong correlation between decreased expression and the poor prognosis." (PMID 39962118, 2025). "The lower mRNA of SERPING1 predicted lower overall survivals and higher malignancy in prostate cancer." (PMID 34790823, 2021). "Notably, SP5’s association with the activation of the AKT/mTOR signal pathway in prostate cancer, hints at intriguing regulatory mechanisms governing SERPING1 transcription that warrant further investigation." (PMID 39962118, 2025). "Therefore, SERPING1 may play an important role in prostate cancer and can serve as a novel marker in prostate cancer diagnosis and prognosis prediction." (PMID 39474998, 2025).
edema (5 papers, 2005 to 2024). An abnormal accumulation of fluid beneath the skin, or in one or more cavities of the body. "Oedemas frequently accompanies the preeclamptic condition, therefore specific malfunctions of SERPINE2 and SERPING1 could represent risk factors for placental diseases." (PMID 16129025, 2005).
tuberculosis (5 papers, 2021 to 2025). A chronic, recurrent infection caused by the bacterium Mycobacterium tuberculosis. "This study evaluates serum ANKRD22 and SERPING1 as potential biomarkers of drug resistance through comparative analysis of expression profiles in drug-resistant versus drug-sensitive tuberculosis patients." (PMID 41261705, 2025). "In a multiple-cohort study of active tuberculosis, increased expression of SERPING1 was identified in patients with active tuberculosis." (PMID 37764178, 2023). "Of note, early systemic elevation of complement subunits followed by elevation of the complement inhibitor SERPING1 has been described in the transition from pre-clinical to active tuberculosis." (PMID 33724185, 2021). "The dual-marker approach involving ANKRD22 and SERPING1 shows promising clinical utility as a potential predictor of tuberculosis drug resistance, offering novel perspectives for improving diagnostic timelines and treatment strategies in drug-resistant TB management." (PMID 41261705, 2025).
Alzheimer disease (4 papers, 2021 to 2024). A progressive, neurodegenerative disease characterized by loss of function and death of nerve cells in several areas of the brain leading to loss of cognitive function such as memory and language. "Interestingly, FTD-Tau patients and late stage Alzheimer’s Disease patients, upregulation of several A1-specific genes (e.g., GBP2, SERPING1, FKBP5) was observed." (PMID 34158119, 2021).
complement deficiencies (4 papers, 2012 to 2025). "The most frequent main genetic causes of complement deficiencies in children infected with SARS-CoV-2 were CFH (n = 3), SERPING1 (n = 3), and FCN3 (n = 2)." (PMID 37559153, 2023).
emphysema (4 papers, 2019 to 2026). "SERPING1 expression was significantly upregulated in both the lung tissue and peripheral blood of patients with COPD, demonstrating negative correlations with lung function and positive correlations with emphysema indices." (PMID 41559025, 2026).
epilepsy (4 papers, 2020 to 2023). A brain disorder characterized by episodes of abnormally increased neuronal discharge resulting in transient episodes of sensory or motor neurological dysfunction, or psychic dysfunction. "We found that in the peripheral whole blood of adult epilepsy patients, SERPING1 was downregulated, whereas miR-328-3p, a circulating microRNA, was upregulated." (PMID 36172025, 2022). "Because SERPING1 is strongly expressed during seizures, it may be a vulnerable epilepsy prediction factor." (PMID 36172025, 2022). "The control of circulating miRNA by SERPING1 may thus play an important role in epilepsy." (PMID 36172025, 2022).
hepatocellular carcinoma (4 papers, 2014 to 2025). A malignant tumor that arises from hepatocytes. "Association of SERPING1 level (Roessler liver array) with clinicopathologic indicators of hepatocellular carcinoma." (PMID 39474998, 2025). "Understanding the intricate molecular and cellular mechanisms underlying SERPING1‐mediated sorafenib resistance could unveil new avenues for complementary therapies in hepatoma treatment." (PMID 39474998, 2025). "Due to the little research on SERPING1 in HCC, we also validated its expression at both the transcriptional and protein levels in hepatocellular carcinoma tissues and cell lines, and we preliminarily verified the cancer‐promoting role of SERPING1 in HCC cells." (PMID 39853609, 2025). "We observed the silencing of SERPING1 and STEAP3 in hepatocellular carcinoma tissues—genes that significantly impact clinical outcome." (PMID 39853609, 2025).
non-Hodgkin lymphoma (4 papers, 2019 to 2025). Distinct from Hodgkin lymphoma both morphologically and biologically, non-Hodgkin lymphoma (NHL) is characterized by the absence of Reed-Sternberg cells, can occur at any age, and usually presents as a localized or generalized lymphadenopathy associated with fever and weight loss. "HAE is caused by mutations in the SERPING1 gene, whereas AAE is typically observed after the age of 40, without a family history and often in association with lymphoproliferative disorders, most notably non-Hodgkin lymphoma (NHL) and monoclonal gammopathies." (PMID 40979805, 2025).
schizophrenia (4 papers, 2018 to 2025). A major psychotic disorder characterized by abnormalities in the perception or expression of reality. "BD has shown a substantial genetic correlation of around 68% with schizophrenia and, interestingly, SERPING1 was among the genome-wide significant risk loci for schizophrenia identified in the largest GWAS of schizophrenia to date (rs9420, p = 2.24×10−9)." (PMID 30379966, 2018). "The most promising variant was located in the gene SERPING1 (p.L349F), which has been reported previously as a genome-wide significant risk gene for schizophrenia." (PMID 30379966, 2018). "The most promising variant was located in the gene SERPING1, which was reported as a genome-wide significant risk gene for schizophrenia in previous research." (PMID 30379966, 2018). "Furthermore, TNFRSF17 (Tier B evidence for schizophrenia) SERPING1 (Tier B evidence for schizophrenia) have approved drugs." (PMID 40281223, 2025).
heart failure (3 papers, 2016 to 2023). Inability of the heart to pump blood at an adequate rate to meet tissue metabolic requirements. "SerpinG1 and SerpinF2 were associated with heart failure in, respectively, two and one out of three EV sub‐fractions and in plasma, but not with renal dysfunction." (PMID 32648717, 2020). "Higher SerpinG1 was directly associated with increased risk of heart failure in TEX sub‐fraction and in plasma, but, inversely associated in the LDL fraction." (PMID 32648717, 2020). "Previously, we reported that EV protein levels of Cystatin C, CD14, SerpinG1, and SerpinF2 were associated with heart failure in dyspnoeic patients." (PMID 32648717, 2020). "SerpinG1 was associated with heart failure, depicted by significant ORs for heart failure and the combination of heart failure and renal dysfunction in LDL and TEX sub‐fraction and in plasma." (PMID 32648717, 2020). "Extracellular vesicle levels of CD14, SerpinG1 and SerpinF2 are associated with the occurrence of heart failure in subjects suspected for acute heart failure, suggesting common underlying pathophysiological mechanisms for heart failure and vascular events." (PMID 26820481, 2016). "In the current study, we found that both SerpinG1 and SerpinF2 were associated with heart failure." (PMID 32648717, 2020). "The primary aim of this study is to investigate the association between the selected EV proteins (Cystatin C, CD14, SerpinG1, and SerpinF2) with both renal dysfunction and heart failure in patients with acute dyspnoea." (PMID 32648717, 2020). "Similar associations between CystatinC (OR 2.01, p = 0.02), CD14 (OR 1.30, p = 0.2) and SerpinG1 (OR 1.43, p = 0.04) and heart failure were found." (PMID 26820481, 2016). "Our multinomial models showed an association for SerpinG1 in the LDL and TEX sub‐fractions and in plasma with heart failure and concurrent heart failure and renal dysfunction, but not with renal dysfunction alone." (PMID 32648717, 2020). "After adjustment for confounders, levels of TEX SerpinG1 (aOR 1.55, p = 0.004) and SerpinF2 (aOR 0.71, p = 0.021) remained statistically significantly related to heart failure, whereas CD14 and CystatinC TEX-levels did not." (PMID 26820481, 2016). "According to these results, SerpinG1 and SerpinF2 seem to be markers for heart failure rather than for renal dysfunction, suggesting that the complement and fibrinolysis pathways may be more important pathophysiologically in development of heart failure than renal dysfunction." (PMID 32648717, 2020).
liver disease (3 papers, 2018 to 2025). "For instance, some of the complement proteins identified in this study, including C1QBP, C4BPA, CLU, and SERPING1, have also been identified in proteomic analyses as potential biomarkers in metabolic dysfunction-associated steatotic liver disease/metabolic dysfunction-associated steatohepatitis." (PMID 38573776, 2024). "Comorbidities such as chronic inflammatory conditions or liver disease could influence the expression of genes like SERPING1 or JUN." (PMID 41137352, 2025).
lung adenocarcinoma (3 papers, 2025 to 2026). A carcinoma that arises from the lung and is characterized by the presence of malignant glandular epithelial cells. "SERPING1 exhibited downregulation in the majority of cancer types, such as colorectal cancer (COAD), lung squamous cell carcinoma (LUSC), lung adenocarcinoma (LUAD), and HCC, whereas it was increased in select malignancies, notably renal clear cell carcinoma (KIRC)." (PMID 39853609, 2025).
lung carcinoma (3 papers, 2019 to 2025). "SERPING1 was upregulated by sorafenib and selected for further study, as it is an independent predictor of survival in lung cancer patients and may be defined as a prognostic marker." (PMID 39474998, 2025).
osteosarcoma (3 papers, 2020 to 2025). A usually aggressive malignant bone-forming mesenchymal neoplasm, predominantly affecting adolescents and young adults. "Among snoRNA co‐expressed genes, we found that SERPING1 is the core gene in the tumorigenesis of osteosarcoma, while it was significantly correlated with the sarcoma overall survival in the present study." (PMID 32780509, 2020).
paroxysmal nocturnal hemoglobinuria (3 papers, 2020 to 2025). Paroxysmal nocturnal hemoglobinuria (PNH) is an acquired clonal hematopoietic stem cell disorder characterized by corpuscular hemolytic anemia, bone marrow failure and frequent thrombotic events. "SERPING1 has long been studied for its role in regulating the complement system, with C1‐inhibitors already used in complement‐related diseases, such as paroxysmal nocturnal hemoglobinuria, and potentially applicable in cancer immunotherapy." (PMID 39853609, 2025).
pneumonia (3 papers, 2016 to 2026). An acute, acute and chronic, or chronic inflammation focally or diffusely affecting the lung parenchyma, caused by an infection in one or both of the lungs (by bacteria, viruses, fungi, or mycoplasma.). "Drug-target analyses suggested that modulation of the complement and coagulation cascades may benefit pneumonia patients with comorbid LC or COPD, highlighting CFB, SERPINA1, and SERPING1 as key candidates and pointing to monocyte-centered pathways as promising therapeutic directions." (PMID 41624060, 2026).
Polypoidal choroidal vasculopathy (3 papers, 2010 to 2015). The presence of aneurysmal 'polypoidal' lesions in the choroidal vasculature. "We aimed to investigate whether variations in SERPING1 are associated with typical AMD or with polypoidal choroidal vasculopathy (PCV) in a Japanese population." (PMID 21526158, 2011).
type 1 diabetes (3 papers, 2018 to 2025). "Furthermore, the differences in F2 and HGFAC, together with associations related to MASP2 and SERPING1, suggest the hypercoagulative state previously reported in type 1 diabetes." (PMID 37537394, 2023). "Intriguingly, aside from the association between SERPING1 and systolic blood pressure, glycosylated hemoglobin (HbA1c), type I diabetes, no discernible link between SERPING1 overexpression and heightened risks of other cardiometabolic conditions and diseases was evident." (PMID 39962118, 2025).
chronic obstructive pulmonary disease (2 papers, 2025 to 2026). A chronic and progressive lung disorder characterized by the loss of elasticity of the bronchial tree and the air sacs, destruction of the air sacs wall, thickening of the bronchial wall, and mucous accumulation in the bronchial tree. "After adjustment, elevated ANKRD22 and SERPING1 remained independent predictors, along with smoking, chronic obstructive pulmonary disease, cavitary disease, previous TB exposure, and treatment interruption." (PMID 41261705, 2025).
glaucoma (2 papers, 2023). Increased pressure in the eyeball due to obstruction of the outflow of aqueous humor. "However, eight proteins (C6, C8G, CFH, C3, CFHR1, CFI, CLU, and SERPING1) were significantly downregulated in Caucasian glaucoma subjects." (PMID 37763167, 2023).
HIV-1 infection (2 papers, 2010 to 2021). The type species of lentivirus and the etiologic agent of acquired immunodeficiency syndrome (AIDS). "As an essential element of the immune system, the complement system can be activated by some viruses, and a previous study indicated that Serping1 and its network serve as important components of the innate immune system to restrict HIV-1 infection." (PMID 34867309, 2021). "SERPING1 (MIM 606860), a regulator of the complement cascade, is also involved in HIV-1 infection (MIM 609423) as its expression is dysregulated in immature dendritic cells by Tat; moreover, the protein product of SERPING1 is cleaved by HCV and HIV-1 proteases." (PMID 20174570, 2010).
leukaemia (2 papers, 2017 to 2023). "Furthermore, our findings indicate up-regulation of genes related to complement (C4A, C4B, and SERPING1) in BM-MSC exposed to leukemia in vivo." (PMID 29137349, 2017).
metastatic disease (2 papers, 2015 to 2019). "Proteins upregulated in serum of patients with metastatic disease included C-reactive protein and IC1 (SERPING1), factors involved in immunity and inflammation, and angiogenin, protein involved in angiogenesis." (PMID 26376850, 2015).
migraine (2 papers, 2024). "However, the associations between SERPING1 and BRH (PP.H4.abf = 0.47), ARHGAP25 and VD (PP.H4.abf = 0.34), PLG and any migraine (PP.H4.abf = 0.30), as well as ISOC1 and VD (PP.H4.abf = 0.06), did not receive sufficient support from co‐localization analysis, with a PP.H4.abf value below 0.5." (PMID 38898596, 2024). "We further found drugs targeted for another six proteins (CSK, FER, GP1BA, PLCG1, PLG, and SERPING1), although currently there are no indications for migraine." (PMID 38898596, 2024).
Obesity (2 papers, 2014 to 2019). Accumulation of substantial excess body fat. "The biological processes “Platelet degranulation,” “Positive regulation of glucose import” and “Cellular response to insulin stimulus,” already found modulated in obesity (PDGFB, SERPING1 ADIPOQ, PIK3R1, IGF1) were further enriched in ObCRC with respect to Ob individuals." (PMID 30838002, 2019).
ocular hypertension (2 papers, 2024). Abnormally high intraocular pressure. "Gene expression of signature astrocyte reactivity markers (Gfap, Lcn2, Steap4, Gbp2, Serping1, and Fbln5) were significantly upregulated in response to ocular hypertension at 2, 4, and 8 weeks compared to that in normotensive controls." (PMID 38610040, 2024).
preeclampsia (2 papers, 2022 to 2024). Preeclampsia is a hypertensive disorder of pregnancy that is characterized by new-onset hypertension with proteinuria presenting after 20 weeks of gestation, and depending on mild or severe forms may initially present with severe headache, visual disturbances, and hyperreflexia. "Intriguingly, unmethylated CpG islands by the transcription start site of SERPING1 have been associated with eight times higher gene expression in placenta tissue from patients with preeclampsia." (PMID 36550527, 2022). "SERPING1 may be involved in the placental circulatory function, the dysregulation of which could lead to vascular leakiness and subsequent edema—which often accompany preeclampsia." (PMID 36550527, 2022).
prion disease (2 papers, 2021 to 2022). A transmissible disease that is caused by a protein that is able to induce abnormal folding of normal cellular proteins, leading to characteristic spongiform brain changes, which are associated with neuronal loss without an inflammatory response. "Increased expression, and possibly, inhibitory activity of SERPING1 in sCJD brains could occur in response to complement activation, already associated to prion diseases." (PMID 35416570, 2022). "Our analysis revealed that, besides the already observed upregulation of SERPINA3 in patients with prion disease and AD, SERPINB1, SERPINB6, SERPING1, SERPINH1, and SERPINI1 were dysregulated in sCJD individuals compared to controls, while only SERPINB1 was upregulated in AD patients." (PMID 35416570, 2022).
sarcoidosis (2 papers, 2022 to 2024). Sarcoidosis is a multisystemic disorder of unknown cause characterized by the formation of immune granulomas in involved organs. "The induced expression levels of the individual genes FCGR1B, GBP1, IFIT2, SERPING1, and UBE2L6 could discriminate between patients with sarcoidosis and TB with a maximum Youden's index >0.80 and corresponding sensitivity >88 % and specificity >89 %." (PMID 39309852, 2024). "Compared to HCs, serum from patients with sarcoidosis significantly (p < 0.05) induced the expression of FCGR1B and IFIT2, whereas serum from patients with TB significantly (p < 0.05) reduced the expression of GBP1, SERPING1, and UBE2L6 compared to HCs." (PMID 39309852, 2024).
sarcopenia (2 papers, 2024 to 2025). Progressive decline in muscle mass due to aging which results in decreased functional capacity of muscles. "Studies have indicated that SERPING1 mitigated the reperfusion injury of skeletal muscle in rats, which may explain its role of alleviating sarcopenia." (PMID 39474649, 2024). "Functional studies using in vitro or in vivo models (e.g., gene knockdown or overexpression) to elucidate the mechanistic roles of key genes such as SERPING1 or IRF7 in HL and sarcopenia." (PMID 41137352, 2025).
spondyloarthritis (2 papers, 2019 to 2025). "Out of the eight co-expressed highly expressed proteins, S100A8, S100A9, SERPING1, CECR1, and FERMT3 are all associated with inflammation, with S100A8 and S100A9 being clinically confirmed to be closely related to spondyloarthritis." (PMID 39877611, 2025). "It is evident that the high expression of S100A8, S100A9, SERPING1, ZYZ, VCL, and FERMT3 is positively correlated with spondyloarthritis." (PMID 39877611, 2025).